HIF1A (hypoxia inducible factor 1 subunit alpha)
Diseases named in the same sentence as HIF1A in open-access papers (continued):
Sharing a sentence is not in itself a finding about the gene and the disease.
cancer (continued). "It has been reported that hypoxia enhances cancer cell invasion through the mediation of hypoxia-inducible factor (HIF)-1α." (PMID 34979904, 2022). "First of all, both HIF-1α and c-Myc participate in glucose feeding of cancer cells by upregulation of the expression of glucose transporter 1 (GLUT1)." (PMID 36340042, 2022). "For the researchers it is intriguing to find therapeutic modalities that can overcome HIF-1α mediated CSC dependent cancer resistance and recurrence." (PMID 36014432, 2022). "HIF-1α is thought to be a key coordinator of cancer cell responses to the hypoxic microenvironment by regulating metabolic reprogramming, angiogenesis, stem cell maintenance, matrix remodeling, metastasis and resistance to chemoradiotherapy." (PMID 36532768, 2022). "Hypoxia-inducible factor (HIF-1α) is a transcription factor that controls metastasis, glucose uptake, angiogenesis, invasion, and cell survival during cancer growth." (PMID 35565972, 2022). "USP29 stabilizes oncogenic MYC (including c-MYC and N-MYC) and hypoxia-induced factor 1α (HIF1α), which are two major drivers of cancer metabolism in normoxia and hypoxia, respectively, by direct interaction and deubiquitination." (PMID 35307036, 2022). "Several natural compounds have been identified as promising therapeutic agents against Ras/Raf/MAPK signaling-driven cancers, impairing HIF-1α formation." (PMID 35890106, 2022). "HIF-1α or HSPA1 L knockdown in a xenograft model inhibited cancer proliferation and liver metastasis." (PMID 35885540, 2022). "As a cell sensor of microenvironment, HIF-1α modulates glycolytic activity to sustain cancer viability and progression." (PMID 35712504, 2022). "HIF1α is broadly expressed and correlates with poor prognosis in human cancers by regulating genes involved in glycolysis, angiogenesis, cell cycle progression, and other cellular pathways." (PMID 36304962, 2022). "The study of HIF-1α as a target for cancer chemotherapy has thus been reported in ≥7500 studies and has progressed rapidly." (PMID 36139362, 2022). "Hif-1α supports cancer cell survival under hypoxic conditions through its activation of nuclear factor kappa B (NF-κB) as well as promotion of expression of ligands for program death receptor 1 (PD-1) and cytotoxic T-lymphocyte-associated protein 4 (CTLA-4)." (PMID 35216362, 2022). "HIF-1α, is a key regulator of cancer-related metabolic pathways, including glycolysis, gluconeogenesis, the Tricarboxylic acid (TCA) cycle, as well as metabolism of nucleotides, amino acids and lipids." (PMID 35391557, 2022). "Several of these specialized TME microenvironments are enriched by the pan-cancer survival network, for example HIF1A signaling (p = 4.27 × 10−6; FGF2, IGF2, MMP1, MMP14, MMP3, PIK3R3, SERPINE1, TGFB1)." (PMID 35106465, 2022). "Sestrin2 can facilitate HIF-1α degradation via AMPK which can contribute to confine cancer cells invasion and metastasis." (PMID 35527284, 2022). "Further studies are necessary to verify its toxic effects and anti-HIF-1α activity in different cancers." (PMID 36014432, 2022). "As a subunit of HIF-1, upregulation of HIF-1α has been reported in various human cancers with unsatisfactory outcomes." (PMID 35927239, 2022). "One of the critical steps in cancer progression cell adhesion seems to be related to the changes of HIF-1α." (PMID 36291742, 2022). "HIF-1α overexpressed under hypoxia is important for the adaptation of cancer cells to the low oxygen concentration of solid tumors within hypoxic regions." (PMID 36080483, 2022). "In non-small-cell lung cancer cells, propofol reduced the aggressiveness of cancer cells by reducing the upregulation of HIF-1α." (PMID 35359377, 2022). "Transcription factor HIF1α has been discovered to control several metabolic enzymes, such as hexokinase and pyruvate dehydrogenase kinase in numerous cancer types, which lead to the Warburg phenotype." (PMID 35298869, 2022).
cancer (continued). "HIF-1α regulates the mitochondrial mass directly and indirectly to overcome the oxidative stress-mediated impairment of cancer growth by activating ubiquitin-dependent and -independent pathways." (PMID 35592530, 2022). "It has been found that HIF-1α is overexpressed in a variety of human cancers, including bladder, liver, breast, lung, osteosarcoma, glioma, ovarian, prostate, colon, and renal cell carcinoma." (PMID 35684364, 2022). "CoCl2 is used in several hypoxia induction studies in which it can induce HIF-1α expression at both mRNA and protein levels in many types of cancers, including MCF-7 cells." (PMID 36080483, 2022). "In dogs, the expression of HIF-1α is increased in several kinds of cancer and has been considered to be a therapeutic target, as well as human cancers." (PMID 36669005, 2022). "We focused our studies on Akt2 and HIF-1α coregulation by MUL1 since activation of these proteins is involved in metabolic phenotypes that favors glycolysis, a hallmark of cancer cells referred to as the Warburg effect." (PMID 35846359, 2022). "There are a number of HIF-1α inhibitors in development as cancer therapeutics, such as EZN-2968, Acriflavine, and LW6." (PMID 36011045, 2022). "In HCC, hypoxia promoted tumorigenesis and cancer stemness through stabilizing and activating hypoxia-inducible factor 1 alpha (HIF-1α)." (PMID 36358763, 2022). "It is well established that autophagy induction is one of the responses of cancer cells to hypoxia, and it is induced by hypoxia-inducible factor 1-alpha (HIF-1α)." (PMID 35912261, 2022). "In these VHL-null tumors, cancer cells are strongly positive for HIF-1α and/or HIF-2α by immunohistochemistry." (PMID 35642641, 2022). "Although the treatment did not satisfy the predefined expectations during the time, it revealed the feasibility of using HIF-1α as a potential target for cancer treatment." (PMID 36003773, 2022). "Another study showed that mir-210 is expressed in different cancer tissues (breast, lung, colon, pancreatic, head, and neck), and correlates with HIF-1α stabilization." (PMID 35741024, 2022). "HIF-1α oncogene is present in numerous malignancies, including ovarian, breast, and bladder cancers, and can induce the glycolytic pathway in malignant tumors." (PMID 36618348, 2022). "The correlation of HIF-1α and β-catenin is commonly detected in cancer and indicates malignant phenotypes." (PMID 34998404, 2022). "The relationship between HIF-1α and NO in cancer angiogenesis appears quite complex and poorly understood." (PMID 36551540, 2022). "Alteration of lipid biosynthesis is another approach of HIF-1α mediated metabolic regulation of cancer cells." (PMID 36014432, 2022). "The authors concluded that the breast CSC marker CD44 was important in the regulation of cancer cell metabolism by modulation of the LDH isoenzymes levels through the HIF-1α." (PMID 36497394, 2022). "2-Methoxyestradiol (2-ME), which has been approved by the US Food and Drug Administration (FDA) to treat several cancers, has been suggested as an HIF-1α inhibitor." (PMID 35456989, 2022). "On the other hand, SRC, CASP3, EGFR, ERBB2, mTOR, MMP9, and HIF1A followed the proteoglycans in cancer (degree 7)." (PMID 35959427, 2022). "Previous studies have shown that GLUT1 transcription is regulated by TEA domain family member 1 (TEAD1), HIF-1α, and c-Myc in proliferative cells like cancer cells and fibroblasts." (PMID 35133975, 2022). "Generally, HIF-1α signaling is thought to promote cancer progression, but in some studies, HIF-1α was shown to be a negative regulator of cancer progression." (PMID 35884382, 2022). "Henceforth, a brief description of different potential anti-cancer natural compounds and synthetic chemotherapeutic agents targeting HIF-1α are discussed in this review." (PMID 36014432, 2022). "HIF-1α increases the uptake of glucose into cancer cells via the transcriptional upregulation of the glucose transporter GLUT1." (PMID 35681691, 2022).
cancer (continued). "The impact of a subunit of hypoxia-inducible factors (HIF-1α) on cancer progression was also investigated using MVN-chip model." (PMID 35158914, 2022). "These pathways related to hypoxia-inducible factors 1 and 2 (HIF1A and HIF2A) and cell-surface signaling (ECM and integrin signalling) both of which have been shown to be implicated in cancer." (PMID 36329531, 2022). "The results suggest that viperin induction via the PI3K/AKT/mTOR/HIF-1α pathway as well as the JAK/STAT pathway allowed cancer cells to rapidly adapt to the changing conditions in the TME through metabolic reprogramming." (PMID 36227691, 2022). "Hypoxia-inducible factor (HIF)-1α is commonly expressed in many cancers because of the hypoxic environment that the cancer metabolic system induces." (PMID 35283421, 2022). "On the other hand, and in contrast to HIF-1α effect on cancer as a stimulator for the disease’s progression, HIF-1α contributes to the cardiac protection in the majority of CVDs." (PMID 35205167, 2022). "Functional mitochondria enable cancer cells to increase glycolytic flux by stabilizing HIF-1α and facilitating its function." (PMID 36292613, 2022). "When cancer cells and tumors are exposed to hypoxia, HIF-1α is stabilized, which subsequently leads to the increased transcription of adenosine-generating ectoenzymes." (PMID 35625561, 2022). "Hypoxia increased HIF-1α level, and changed the morphology, viability, and metastatic potential of cancer cells." (PMID 35158914, 2022). "Expression of HIF1α is commonly regulated by hypoxia, but, particularly in cancer, can also be modulated by other factors, such as inhibitors of mammalian target of rapamycin (mTOR)." (PMID 36093095, 2022). "It is already known that Akt and HIF-1α crosstalk, especially in cancer, resulting in combined or enhanced effects." (PMID 35163310, 2022). "Hypoxia-activated HIF-1α induces cancer EMT through multiple molecules and pathways, including epigenetic regulators and transcription factors/repressors." (PMID 36071871, 2022). "Even though ACF is an FDA approved drug for urinary tract infections, recent research proved its anti-cancer efficacy which involves inhibition of HIF-1α activity." (PMID 36014432, 2022). "Histone demethylase jumonji C domain-containing 2 C (JMJD2C) has been shown to serve as a co-activator for HIF-1α in cancer progression." (PMID 36326232, 2022). "The critical regulators of the glycolytic pathway, HK-II, PKM2, and HIF-1α that contribute to the metabolic reprogramming in cancer cells also showed a profound increase in the OPM-BMG cells in comparison to BMG-1 cells." (PMID 36591481, 2022). "Intriguingly, staining for HIF1A, a major glycolytic regulator in cancers, was found exclusively in the PSN1 tumors with typical nuclear expression pattern in the cancer cells." (PMID 36494842, 2022). "In this work, the authors showed that IL-1β induced the epithelial-to-mesenchymal transition of cancer cells through the hypoxia-inducible factor 1α (HIF-1α), thereby initiating the metastatic process." (PMID 36551635, 2022). "Our results found that there were differences in the mRNA expression levels of HIF1α in human pan-cancer and its corresponding normal tissues." (PMID 35860430, 2022). "Hypoxia, a common phenomenon in malignant tumors, speeds up cell proliferation regulated by HIF-1α expression." (PMID 36246557, 2022). "In response to both hypoxic stress and oncogenic signals, HIF-1α becomes activated and controls different mechanisms involved in cancer cell survival and proliferation resulting in the formation of vascular tumors with metastatic potential." (PMID 36014432, 2022). "Pharmacological research suggested that CA, an active ingredient extracted from Cinnamon, can inhibit the angiogenic activity of cancer by regulating the mTOR pathway‐mediated suppression of HIF‐1α expression." (PMID 34964259, 2022).
cancer (continued). "Firstly, Zhong and colleagues provided clinical evidence indicating that HIF-1α plays a critical role in the growth and metastasis of several human cancers." (PMID 35592530, 2022). "Overall, we found that matrix detachment modulates the epigenome during anoikis, inducing KDM6A/B that positively regulates the expression of SOX2, CD44, and HIF1α to regulate survival and stemness of cancer cells." (PMID 35186918, 2022). "Adaptation of cancer cells to the hypoxic microenvironment is regulated through physiological responses to hypoxia that are mediated by hypoxia-inducible factors, namely HIF-1α and HIF-2α." (PMID 35328549, 2022). "HIF-1α derived from M2 macrophages elevates the secretion of CXCR4 in cancer cells to promote colorectal liver metastasis." (PMID 35251974, 2022). "HIF-1α is a master regulator of oxygen homeostasis involved in different stages of cancer development." (PMID 35629169, 2022). "Urokinase plasminogen activator receptor (uPAR), transcriptionally activated by HIF-1α, increases the metastatic potential of cancer cells under hypoxic conditions." (PMID 35884382, 2022). "Because HNK has an antioxidant effect and HIF-1α is the key molecule of oxygen sensing in cells, we are interested in understanding how HNK and HIF-1α synergistically regulate energy metabolism in cancer cells." (PMID 35350760, 2022). "The expression of HIF-1α in cancer results in gene stability, which leads to the promotion of cell growth, proliferation, invasion/metastasis and metabolic adaptation in a hypoxic condition." (PMID 35283421, 2022). "Cancer cells can switch from their aerobic metabolism to the glycolytic pathway by increasing the expression of hypoxia-inducible factor-1α (HIF-1α)." (PMID 35350760, 2022). "HIF-1α, on the other hand, was attributed a protective effect against ferroptosis in several cancer cells by reducing iron and ROS levels, promoting lipid storage and regulating lipid metabolism." (PMID 35906211, 2022). "Among these transporter proteins, GLUT1 and GLUT3, induced by hypoxia-inducible factor 1α (HIF-1α), have been shown to potentiate glycolysis and cancer progression." (PMID 35958586, 2022). "Cancer cell death has been inhibited by HIF-1α stabilization and activation in the adaptation of cells to SD-induced oxidative stress." (PMID 36498831, 2022). "The VHL binding protein DJ1 regulates the function of HIF-1α in both cancer and neuronal cells through binding VHL and limiting HIF-1α degradation." (PMID 35269911, 2022). "Several studies have described NO’s effect on HIF-1α accumulation and metabolic profile in cancer and somatic cells." (PMID 35326146, 2022). "In order to determine the nonphysiological oxygen tension level (hypoxia) in the TME, we have evaluated the level of expression of HIF-1α in both cancer and normal tissues." (PMID 35496046, 2022). "WSB1 promotes cancer progression by affecting the Von Hippel–Lindau tumor suppressor protein (pVHL) and upregulating hypoxia inducible factor-1α (HIF-1α) target gene expression." (PMID 35600960, 2022). "In glioma stem cells (GSCs), apigenin downregulated the expression of GLUT-1/3, NF-κB and PKM2 by inhibiting the expression of HIF-1α, inhibited the glycolysis process of cancer cells, and increased the radiosensitivity of GSCs." (PMID 36339566, 2022). "Colon cancer has a better prognosis than other cancer types because it has higher levels of macrophage infiltration and HIF-1α expression." (PMID 36071472, 2022). "A downstream target of HIF1α that is known to contribute to hypoxia-induced metabolic adaptation of cancer cells is the pro-glycolytic factor GLUT1." (PMID 36340043, 2022).
cancer (continued). "Another glycolytic pathway member, Hexokinase 2(HK2), is a rate limiting enzyme involved in phosphorylation of glucose to glucose-6-phosphate and also reported to be up-regulated by HIF-1α in hypoxic cancer cells." (PMID 36014432, 2022). "Markedly, both cancer cell lines already exhibiteda high level of HIF-1α, suggesting a nearly hypoxic conditionwithin the cell, able to stabilize HIF-1α." (PMID 36445323, 2022). "A careful examination of some cell functions influenced by HIF1A-targeting MIR31HG is warranted to provide more evidence for their impacts on cancer cells in the future." (PMID 36230902, 2022). "Accumulated evidence has shown that EGFR activation increases the expression of HIF-1α in cancer cells under normoxic conditions." (PMID 36435833, 2022). "Given that HIF-1α mediates metabolic alteration in cancers, we believe that viperin is a novel downstream molecule of the HIF-1α signaling pathway." (PMID 36227691, 2022). "Under hypoxia, cancer cells express HIF-1α, which helps to increase adenosine accumulation, but NK cells have impaired killing ability and lowered expression of NKG2D and intracellular perforin and granzyme B." (PMID 35815945, 2022). "It is widely accepted that HIF1α and HIF2α play partially overlapping roles in different types of cancer cells." (PMID 35054927, 2022). "Through the analysis of ChIP-seq data in eight cancer cell lines, we identified 201 potential HIF1A cofactors." (PMID 36347941, 2022). "For instance, lincRNA-p21 binds von Hippel-Lindau (VHL) protein and HIF-1α separately, disrupting their interaction and stabilizing HIF-1α to enhance glycolysis in cancer cells." (PMID 35659362, 2022). "Baicalein is more potent in inhibiting cancer cell viability as well as the expression of HIF-1α, vascular endothelial growth factor, cMyc, and NF-κB." (PMID 36432119, 2022). "Taken together, cancer cells activate a metabolic switch that involve HIF-1α and impaired Krebs cycle and OXPHOS function to sustain glycolysis metabolism." (PMID 35205167, 2022). "Different types of cancers in the breast, colon, lung, prostate and ovary have regulation of HIF-1α; therefore, these cancers can be controlled by targeting this specific protein." (PMID 36014432, 2022). "In this context, the accumulation of α‐ketoglutarate (αKG) and of intramitochondrial oxygen favor the degradation of hypoxia‐inducible factor 1α (HIF‐1α), the key regulator of hypoxic responses, thus reducing cancer growth both in vitro and in vivo." (PMID 34606156, 2022). "The HIF-1α inhibitor echinomycin potentiated the cancer immunotherapeutic effects of anti–CTLA-4 therapy, with efficacy comparable to that of anti–CTLA-4 plus anti–PD-1 antibodies." (PMID 35239514, 2022). "Melatonin also suppresses hypoxia-induced cancer cell migration and invasion through the inhibition of HIF-1α due to its antioxidant impact on hypoxia." (PMID 36009340, 2022). "RUNX3 plays an anti-angiogenic role through the degradation of HIF-1α under hypoxia or the direct suppression of VEGF gene expression in cancers." (PMID 36231060, 2022). "It is reported that PKM2 acts as a coactivator of HIF-1α to regulating glucose metabolism in cancer cells." (PMID 36514094, 2022). "This process is HIF-1α dependent as deletion of HIF1α in adipocytes blunts lipid release and access of lipids to cancer cells." (PMID 36329893, 2022). "The HIF-1α-mediated metabolic switch occurs not only in cancer cells but also in immune cells in the TME, promoting the immune inhibitory macrophage M2-like phenotype of TAMs and impairing innate immunity natural killer (NK) cell activity." (PMID 36276103, 2022). "The expression of HIF-1α in cancers can lead to cell growth, proliferation, invasion/metastasis and immune escape." (PMID 35283421, 2022). "Studies have indicated that CoCl2 can promote EMT by stabilizing HIF-1α (a key hypoxia marker) in various cancer cell lines." (PMID 35897065, 2022).